ITGA5 (integrin subunit alpha 5)
Diseases named in the same sentence as ITGA5 in open-access papers (continued):
Sharing a sentence is not in itself a finding about the gene and the disease.
glioma (26 papers, 2017 to 2025). A benign or malignant brain and spinal cord tumor that arises from glial cells (astrocytes, oligodendrocytes, ependymal cells). "Remarkably, ITGA5 was observed to influence the immune cell infiltration and immune microenvironment in gliomas, with higher levels of immune cell infiltration associated with elevated ITGA5 expression." (PMID 38903179, 2024). "In particular, a direct interaction between IGFBP2 and ITGA5 has been observed in glioma cells, and this association is required for IGFBP2-regualted cell mobility." (PMID 38918360, 2024). "In glioma, ITGA5 was implicated in immune-related processes, distinct typical genomic alterations and key oncogenic pathways." (PMID 38903179, 2024). "Further studies exploring the role and mechanism of ITGA5 will endow great potential for the development of diagnostic and anti-glioma therapeutic strategies." (PMID 35371978, 2022). "In conclusion, the higher ITGA5 abundance was closely associated with a higher mortality hazard in glioma patients." (PMID 35371978, 2022). "A higher expression level of ITGA5 was associated with poorer outcomes in patients with glioma (TCGA: HR = 5.564, 95%CI = 4.203–7.367, p < 0.0001; CGGA: HR = 2.899, 95%CI = 2.433–3.454, p < 0.0001)." (PMID 34976814, 2021). "It has also been reported that high ITGA5 expression is associated with high immune cell infiltration in gliomas, and these patients may benefit from immune checkpoint blockade." (PMID 39857068, 2025). "Elevated ITGA5 level was tightly linked to the survival detriment of gliomas patients." (PMID 35371978, 2022). "However, few studies have explored the association between tumor immune microenvironment and ITGA5 expression level in gliomas." (PMID 35371978, 2022). "Although NEAT1, miR-128-3p, and ITGA5 have been widely implicated in various tumors, their relationship remains largely unknown in glioma." (PMID 34263426, 2021). "Moreover, the reduced methylation on ITGA5 was associated with poorer outcomes in glioma patients, reinforced by the survival analysis." (PMID 34976814, 2021). "At present, ITGA5 has been reported to have poor prognosis in many tumors including glioma, pancreatic cancer, Oral Squamous Carcinoma, bladder cancer." (PMID 38526326, 2024). "Previous studies have found that FN1 as well as ITGA5 could facilitate tumor angiogenesis and progression in cervical cancer and may be a prognostic risk factor in many types of cancer including Gliomas, gastric cancer, head and neck squamous cell carcinoma and NSCLC." (PMID 38730286, 2024). "Meanwhile, ITGA5 orchestrated the process of proliferation inhibition induced by tocopherols of glioma cells." (PMID 35371978, 2022). "Firstly, we analyzed 3,047 glioma patient samples collected from the TCGA, the CGGA, and the GEO databases, proving that high ITGA5 expression positively related to aggressive clinicopathological features and poor survival in glioma patients." (PMID 35371978, 2022). "Immunohistochemistry (IHC) staining was performed to detect the representative PTK2 and ITGA5 protein levels in gliomas and peritumor tissues (16 cases) obtained from patients treated at The Second Hospital of Shandong University." (PMID 36091049, 2022). "The results of the submap showed that the high- and low-ITGA5 groups had different responses to immunotherapy in that the high-ITGA5 group had a significant response to anti-PD-1 immunotherapy in gliomas based on the TCGA." (PMID 35371978, 2022). "Subsequently, the TCGA-based and the CGGA-based KM curves more firmly demonstrate the severe survival detriment in glioma patients with high ITGA5 expression." (PMID 35371978, 2022). "Altogether, our comprehensive analyses deciphered the prognostic, immunological, and therapeutic value of ITGA5 in glioma, thus improving individual and precise therapy for combating gliomas." (PMID 35371978, 2022).
glioma (continued). "In this study, we comprehensively investigated the ITGA5 expression patterns in gliomas based on genomic and transcriptional profiles with complete clinical annotations." (PMID 35371978, 2022). "Overall, the high expression of ITGA5 supplied a fertile niche favoring glioma progression by activating oncological signaling pathways and immune reprogramming." (PMID 35371978, 2022). "The conspicuously impaired survival in high-ITGA5 groups was observed in 7 independent glioma sets from the GEO database as well." (PMID 35371978, 2022). "We observed that ITGA5 was involved in pivotal oncological pathways, immune-related processes, and distinct typical genomic alterations in gliomas." (PMID 35371978, 2022). "In the present study, by comprehensive bioinformatic analysis, we identified that ITGA5 was positively related to aggressive clinicopathological and molecular features in gliomas." (PMID 35371978, 2022). "ITGA5 was regulated in glioma cells and mediated glioma cell dispersion and invasion by cell–matrix and cell–cell interactions." (PMID 35371978, 2022). "Collectively, our comprehensive analyses deciphered the prognostic, immunological, and therapeutic value of ITGA5 in glioma management, thus providing a target for individual and precise therapy for combating gliomas." (PMID 35371978, 2022). "The results exhibited an intimate connection between ITGA5 and most immune checkpoint molecules in gliomas, especially in programmed cell death 1 (PD-1), programmed cell death 1 ligand 1 (PD-L1), and cytotoxic T-lymphocyte associated protein 4 (CTLA-4)." (PMID 35371978, 2022). "Consistent with the previous results, ITGA5 protein levels were significantly increased in glioma compared to peritumor tissue, whereas PTK2 levels were decreased in tumors." (PMID 36091049, 2022). "As expected, the adverse prognostic impacts of ITGA5 were obtained from 7 independent glioma sets from the GEO database." (PMID 35371978, 2022). "It is particularly noteworthy that ITGA5 is involved in remolding glioma immune infiltration and TME that is closely related to immunotherapy." (PMID 35371978, 2022). "In summary, our findings demonstrated that ITGA5 is upregulated in glioma and differs in multiple molecular phenotypic gliomas, acting as a potential biomarker for predicting glioma prognosis." (PMID 35371978, 2022). "Subsequently, we evaluated the role played by ITGA5 with miR-128-3p in glioma cells with regard to cell proliferation, migration, invasion, apoptosis, and cell cycle of GBM cell lines." (PMID 34263426, 2021). "Although abnormalities of NEAT1, miR-128-3p, or ITGA5 expression have been reported in various studies about glioma, their potential interaction remains a puzzle." (PMID 34263426, 2021). "Taken together, our studies provide novel insights into the NEAT1/miR-128-3p/ITGA5 axis in glioma, and are expected to guide future development of therapies for glioma treatment." (PMID 34263426, 2021). "ITGA5 was augmented in TMZ-resistant glioma cells, while overexpressing ITGA5 altered the cell-promoted TMZ resistance through enhancing vascular mimicry (VM) formation correspondingly." (PMID 34976814, 2021). "The expression level of ITGA5 was significantly higher in glioma tissues compared to that in normal brain tissue and steadily increased with advancing glioma grade." (PMID 34976814, 2021). "The expression level of ITGA5 was effective in determining drug resistance and the outcome of glioma patients, which is regulated by methylation on two distinct sites." (PMID 34976814, 2021). "To determine the possible contribution of ITGA5 in drug resistance, we systematically analyzed the transcriptomic data of glioma patients from TCGA and CGGA databases and normal brain samples from the GTEx database." (PMID 34976814, 2021). "Consistent with this, more abundant ITGA5 protein was observed in high-level gliomas than in low-level gliomas based on the immunohistochemistry staining files from THPA database." (PMID 34976814, 2021).
glioma (continued). "Further experiments suggested that ITGA5 expression was increased in glioma tissues and was found to be connected with miR-128-3p." (PMID 34263426, 2021). "Our studies demonstrated the antioncogenic effects of miR-128-3p, as well as pro-oncogenic impacts of NEAT1 and ITGA5 in glioma cells." (PMID 34263426, 2021). "Of these, ten genes (CTSZ, EFEMP2, ITGA5, KDELR2, MDK, MICALL2, MAP 2 K3, PLAUR, SERPINE1 and SOCS3) can potentially classify patients with gliomas into different risk groups." (PMID 32878880, 2020). "Increasing expression of circPTN rescued the inhibition of proliferation and downregulation of SOX9/ITGA5 in glioma cells by miR-145-5p/miR-330-5p." (PMID 31511040, 2019). "Furthermore, ITGA5 has been shown to be an important biomarker in predicting temozolomide and bevacizumab resistance in gliomas." (PMID 39857068, 2025). "Interestingly, high ITGA5 expression has been shown to be positively related to aggressive clinicopathological features and poor survival in glioma patients." (PMID 38612755, 2024). "ITGA5 mediates glioma cell dispersal and invasion through cell-matrix and cell–cell interactions." (PMID 37015905, 2023). "Thus, the GDSC database was adopted to assess the drug response of high-ITGA5 and low-ITGA5 glioma groups, and the predictive accuracy was measured by 10-fold cross-validation." (PMID 35371978, 2022). "Additionally, the uni-Cox and multi-Cox analyses indicated that ITGA5 was the independent indicator for the mortality in glioma patients." (PMID 35371978, 2022). "Our results showed that FN1, ITGA5, OSMR, and NGFR were overexpressed in TCGA-GBM, suggesting that these genes were not only prognostic but also diagnostic between high-grade gliomas and normal brain tissue." (PMID 35954323, 2022). "Besides, we also proved that high-ITGA5 gliomas were accompanied by high immunotherapy biomarker expression, namely, PD-1, PD-L1, CTLA-4, and VEGF, thus showing an ITGA5-targeted therapeutic potential to be synergistic with immunotherapy." (PMID 35371978, 2022). "Notably, ITGA5 was found to engage in remolding glioma immune infiltration and immune microenvironment, manifested by higher immune cell infiltration when ITGA5 is highly expressed." (PMID 35371978, 2022). "The results showed that EMP3 and ITGA5 were most commonly genomically altered and may be involved in glioma progression." (PMID 35647198, 2022). "Consistently, our results also revealed that ITGA5 might be an oncogenic factor, presuming that the high ITGA5 expression possibly indicated a low survival rate in glioma patients." (PMID 35371978, 2022). "In gliomas, the ITGA5 transcriptional levels increased with more adverse clinicopathological characteristics, namely, greater age at diagnosis, 1p/19q non-codeletion, higher grade, wild-type isocitrate dehydrogenase (IDH) status, unmethylated MGMT status, and mesenchymal subtype." (PMID 35371978, 2022). "IDH mutation is a classic prognostic indicator in judging glioma, and there is a certain negative correlation between ITGA5 expression level and IDH mutation level." (PMID 35371978, 2022). "Thus more comprehensive studies are needed to further interpret the role of ITGA5 in gliomas immunology." (PMID 35371978, 2022). "The NEAT1/miR-128-3p/ITGA5 axis is essential in the genesis and development of glioma and may be a viable innovative technique for glioma treatment." (PMID 36793341, 2022). "Moreover, ITGA5 was relevant to distinct genomic alterations and tumor immune microenvironment in gliomas." (PMID 35371978, 2022). "Chen reported a phenomenon that the ITGA5 downregulation could inhibit the glioma proliferation, which could be rescued by circPTN." (PMID 35371978, 2022). "Moreover, the ITGA5 amplification in gliomas with high-grade or invasive molecular signatures was validated both in the TCGA and the CGGA cohorts." (PMID 35371978, 2022).
glioma (continued). "Among these cells, immunosuppressive cells such as Tregs and myeloid-derived suppressor cells were increased more significantly with the increase of ITGA5 expression, suggesting that ITGA5 was essential in the formation of glioma immunosuppressive microenvironment." (PMID 35371978, 2022). "Moreover, both the epigenetic and transcriptional levels of ITGA5 are effective in predicting TMZ and bevacizumab resistance, revealing the novel roles of ITGA5 in predicting the treatment outcomes of glioma." (PMID 35954323, 2022). "Overall, these results suggested that miR-128-3p could suppress tumor-promoting effects of ITGA5 in glioma cells." (PMID 34263426, 2021). "Interestingly, ITGA5 has been previously shown to be a tumor promoter in multiple tumor types, including glioma." (PMID 34263426, 2021). "Besides, a significant phosphorylation of FAK was observed in cells overexpressing ITGA5, indicative of high migration and invasion of glioma cells." (PMID 34263426, 2021). "Meanwhile, ITGA5 mitigated and restored miR-128-3p-induced adverse effects in glioma cell lines." (PMID 34263426, 2021). "In addition, the epithelial features were decreased with increased mesenchymal genes in ITGA5-overexpressing cells, suggesting that ITGA5 promoted the EMT process in glioma cells." (PMID 34976814, 2021). "Collectively, these results indicated that the NEAT1/miR-128-3p/ITGA5 axis was involved in glioma initiation and progression, and might offer a potential novel strategy for treatment of glioma." (PMID 34263426, 2021). "Finally, the glioma patients with higher expression of ITGA5 may present better outcomes of chemotherapy treatment, namely, bexarotene, bicalutamide, and bortezomib, which provided more therapeutic choices in the future." (PMID 35371978, 2022). "In addition, the inhibitor of ITGA5 attenuates glioma growth and cell dispersion." (PMID 35371978, 2022). "Moreover, Kita also confirmed that ITGA5, which was upregulated by Ets-1, could be secreted by glioma cells to boost tumor migration and invasion, finally contributing to glioma malignancy." (PMID 35371978, 2022). "New studies have found that some biomarkers, such as ITGA-5 and Tenascin-C, could predict glioma prognosis, and are closely related to the immunosuppressive microenvironment, particularly for the clinical application of immunotherapy in glioma." (PMID 35812432, 2022). "Four stiffness-dependent prognostic genes (FN1, ITGA5, OSMR, and NGFR) were identified from GSE158097 and TCGA glioma datasets using bioinformatics analysis." (PMID 35954323, 2022). "We further explored the relationship between ITGA5 and some immune checkpoints, such as PDCD1 (PD-1), CD274 (PD-L1), and PDCD1LG2 (PD-L2) in gliomas based on the TCGA dataset." (PMID 35371978, 2022). "After validation using the Chinese Glioma Genome Atlas (CGGA) database, we further identified four stiffness-dependent prognostic genes: FN1, ITGA5, OSMR, and NGFR." (PMID 35954323, 2022). "Therefore, ITGA5 could be exploited as a powerful indicator of clinical outcomes in gliomas." (PMID 35371978, 2022). "Based on further validation using the Chinese Glioma Genome Atlas (CGGA) database, we identified FN1, ITGA5, OSMR, and NGFR as stiffness-dependent prognostic genes." (PMID 35954323, 2022). "To further evaluate the sensitivity of ITGA5 to immunotherapy, we applied the TIDE and the submap algorithms to glioma patients in the TCGA." (PMID 35371978, 2022). "In addition, we also found that ITGA5 was significantly positively correlated with VM-related genes, especially with genes coding collagen and other ECM components, indicating that ITGA5 may increase the degree of malignancy and drug resistance of glioma by affecting VM formation." (PMID 34976814, 2021). "In this study, we analyzed public data to prove the value of ITGA5 in predicting responses to TMZ and Bevacizumab and investigated the role of ITGA5 in mediating VM formation in glioma." (PMID 34976814, 2021).
glioma (continued). "Firstly, qRT-PCR was performed to analyze levels of ITGA5 expression in glioma samples; the results showed that it progressively increased from NBT to LGG and HGG, indicating a close correlation between ITGA5 and tumor grades." (PMID 34263426, 2021). "It was showed that ITGA5 and ITGB3 are expressed in glioma vessels and tumor cells and the gene expression is significantly associated with the malignancy grade of the tumor and poor patient prognosis." (PMID 33036421, 2020). "Furthermore, our previous study showed that ITGA5 expression predicted dual resistance to TMZ and bevacizumab in glioma by promoting vascular mimicry and cell survival." (PMID 38887185, 2024). "MES-like glioma cells expressed multiple receptors for ANGPTL4, including SDC2 SDC3, SDC4, and integrins ITGA5 and ITGB1, suggesting that the ANGPTL pathway may be responsible for the enrichment of GSCs in ECMhi tumors." (PMID 37884531, 2023). "miR-27b/ ITGA5 axis participated in the regulation of tongue squamous cell carcinoma epithelial-mesenchymal transition and lncRNA NEAT1/ miR-128-3p/ITGA5 axis was involved in the regulation of glioma progression." (PMID 36742137, 2023). "High GNAI, EMP3, TIMP1, ITGA5, and NMI while low PCDH7, CALCRL, and NFKBIA expressions could lead to poor prognoses in glioma patients." (PMID 35647198, 2022). "Overall, given the pivotal role of ITGA5 in malignancies, we hypothesized that a comprehensive elucidation of the ITGA5-related multi-omics landscape, especially TME contexture, may favor the deeper understanding of the gliomas pathogenesis and progression." (PMID 35371978, 2022). "In summary, ITGA5-induced VM may promote resistance to TMZ and Bevacizumab by altering glioma vascularization." (PMID 34976814, 2021). "Both the epigenetic and transcriptional levels of ITGA5 are effective in predicting TMZ and Bevacizumab resistance, indicating that ITGA5 may serve as a predictor of the treatment outcomes of glioma patients." (PMID 34976814, 2021). "The quantitative real-time PCR method was used to evaluate mRNA expression of SEMA3(A-G), neuropilins (NRP1 and NRP2), plexins (PLXNA2 and PLXND1), cadherins (CDH1 and CDH2), integrins (ITGB1, ITGB3, ITGA5, and ITGAV), VEGFA and KDR genes in 59 II-IV grade glioma tissues." (PMID 33036421, 2020). "Specifically, ITGA5 may promote the growth of glioma cells via the FAK signaling pathway without decomposition by miR-128-3p." (PMID 35647198, 2022). "Notably, ITGA5 was depleted by miR-128-3p, whereas NEAT1 would forestall that and sponge miR-128-3p competitively so that ITGA5 could activate FAK signaling pathway and facilitate glioma progression." (PMID 34263426, 2021).